FFAR2 (free fatty acid receptor 2)
Diseases named in the same sentence as FFAR2 in open-access papers (continued):
Sharing a sentence is not in itself a finding about the gene and the disease.
keratitis (1 paper, 2026). A corneal disease that is characterized by inflammation of the cornea. "Our findings corroborated with previous studies where FFAR2 knockdown has shown enhanced susceptibility to C. rodentium, Klebsiella pneumoniae lung infection, and TLR-induced keratitis." (PMID 41358724, 2026).
periodontal disease (1 paper, 2020). "Taken together, the data presented suggest that FFAR2 recognition of P. gingivalis-derived SCFA may be of particular relevance as pro-inflammatory mediators operating during periodontal disease, and that this neutrophil specific phenomenon could help explain the dominance of neutrophils in GCF." (PMID 33542906, 2020).
peripheral artery disease (1 paper, 2020). "Several genes were previously shown upregulated in circulating leukocytes in patients with peripheral artery disease (FCAR, FFAR2, DUSP5, PLAUR)." (PMID 31875423, 2020).
placental disorders (1 paper, 2024). "We believe the findings of this study will provide a better understanding of the role of SCFAs in placental growth and development during pregnancy and highlight the potential of FFAR2 as a therapeutic target for placental disorders in the future." (PMID 39526775, 2024).
Retinal atrophy (1 paper, 2026). A nonspecific term denoting wasting, especially as a result of degeneration, of the retinal pigment epithelium (RPE) and neurosensory retinal cells. "PBA and NaAc treatment in mice attenuated the ZIKV-induced ocular manifestations (intraocular pressure, RPE/retinal atrophy, and TM/anterior segment inflammation), which was abrogated by FFAR2 inhibition by 4-CMTB, a selective pharmacological inhibitor of FFAR2." (PMID 41358724, 2026).
triple-negative breast carcinoma (1 paper, 2017). An invasive breast carcinoma which is negative for expression of estrogen receptor (ER), progesterone receptor (PR), and human epidermal growth factor receptor 2 (HER2). "Here, both FFAR2 and FFAR3 gene expression was significantly downregulated in invasive and triple negative breast cancer tissues when compared to normal breast tissues." (PMID 29049318, 2017).
ZIKV infection (1 paper, 2026). "Together, our results indicate that PBA and NaAc mediate their antiviral activity via FFAR2 signaling, and inhibition of FFAR2 dramatically enhances the HTMCs susceptibility towards ZIKV infection." (PMID 41358724, 2026). "However, the role of SCFAs and their receptor FFAR2 in ZIKV infection and associated inflammatory immune responses has never been demonstrated." (PMID 41358724, 2026). "To assess the role of FFAR2 in HTMCs, we pretreated the cells with PBA and NaAc prior to ZIKV infection and measured the expression of FFAR2 via qPCR, western blotting, and immunofluorescence staining." (PMID 41358724, 2026).
tumor (46 papers, 2016 to 2026). "By quantifying the cross-sectional area, it was found that the adipose tissue in tumor-bearing mice was significantly reduced in size (P < 0.001), while PL (P < 0.05), PH (P < 0.01), gavage, and FFAR2 (P < 0.001) predominantly prevented fat loss." (PMID 40129936, 2025). "The microbial metabolite-sensing receptor FFAR2 is critical for the regulation of immune cell function and the maintenance of gut homeostasis, and the loss of FFAR2 increases tumor burden in multiple models of tumorigenesis." (PMID 34234806, 2021). "In addition, FFAR2 deficiency markedly restrained tumor growth and prolonged the survival of syngeneic LLC mouse model." (PMID 38402237, 2024). "Here, we report a significant accumulation of SCFAs (acetic acids) in both patients and mouse tumor tissues, and FFAR2 activated by acetic acids in a more immune suppressive MDSCs, which are proven essential for immune suppression and cancer progression." (PMID 38402237, 2024). "Ligands for FFAR2 (G protein-coupled receptor 43, GPR43) inhibit the TNF-α signaling pathway, thus FFAR2 − TNF being upregulated signifies the suppressive effect of VCAN+ TAMs on anti-tumor immunity." (PMID 39232806, 2024). "In this study, we disclose the accumulation of acetic acids in TME, the tumor cell metabolites to enhance the immunosuppressive activity of FFAR2 expression MDSCs." (PMID 38402237, 2024). "Whole or myeloid Ffar2 gene deletion markedly restrained tumor progression, and impairs the immunosuppressive activity of MDSCs to reconstitute a more anti-tumoral TME." (PMID 38402237, 2024). "Here we showed the fundamental role of extraordinary accumulated acetic acids in cancer cells induced immune evasion through consuming L-Arginine in tumor microenvironment by FFAR2+ MDSCs." (PMID 38402237, 2024). "Surprisingly, whole or myeloid Ffar2 gene deletion markedly inhibited urethane-induced lung carcinogenesis and syngeneic tumor growth with reduced MDSCs and increased CD8+ T cell infiltration." (PMID 38402237, 2024). "Collectively, these data suggest that FFAR2 deletion impairs the immunosuppressive activity of MDSCs on T cells in the tumor microenvironment." (PMID 38402237, 2024). "Collectively, these data demonstrate the predominant role of FFAR2 in acetic acids promoted tumor progression." (PMID 38402237, 2024). "FFAR2 deficiency significantly attenuated Gr-1+ MDSC infiltration in urethane-induced mice lung tumor tissues, LLC and B16F10 tumor tissues." (PMID 38402237, 2024). "To evaluate the potential of FFAR2 inhibition in immune checkpoint therapy, we treated tumor bearing mice with FFAR2 inhibitor (GLPG0974) with or without anti-PD-1 antibody." (PMID 38402237, 2024). "The re-expression and activation of this receptor in CRC cells inhibited proliferation and induced apoptosis and cell cycle arrest, providing evidence that FFAR2 functions as a tumor suppressor." (PMID 33897470, 2021). "We uncovered FFAR2, an epigenetic tumor suppressor, as potentially responsible for the inability of MLL-AF4 to immortalize adult cells under myeloid conditions." (PMID 32517300, 2020). "Additionally, research has revealed that short-chain fatty acids (SCFAs) produced by Fn can regulate Th17 responses in an FFAR2-dependent manner, suppressing anti-tumor immune cells and facilitating tumor angiogenesis." (PMID 40370465, 2025). "The combination therapy strategy of FFAR2 pharmaceutical inhibition with anti-PD-1 antibody demonstrated superior antitumor effectiveness to anti-PD-1 antibody therapy alone in LLC subcutaneous mouse tumor model." (PMID 38402237, 2024). "Mechanistically, FFAR2 deficiency in MDSCs significantly reduced the expression of Arg1 through Gαq/Calcium/PPAR-γ axis, which eliminated T cell dysfunction through relieving L-Arginine consumption in tumor microenvironment." (PMID 38402237, 2024).
tumor (continued). "Furthermore, not only the accumulation of L-Arginine was enhanced significantly in the tumor from FFAR2 conditional knock mice, but also the consuming of L-Arginine was hampered significantly in FFAR2 knockout MDSCs." (PMID 38402237, 2024). "Metabolite profiling revealed a significant accumulation of acetic acids in tumor tissues from both patients and mouse model, which contribute to immune suppression and cancer progression significantly through free fatty acid receptor 2 (FFAR2)." (PMID 38402237, 2024). "Furthermore, MDSCs deletion in vivo, co-injection of MDSCs with tumor cells and myeloid cell conditional knockout Ffar2 mouse tumor models showed that FFAR2 drive tumor progression mainly through MDSCs." (PMID 38402237, 2024). "Although the LLC tumor growth was restrained by FFAR2 inhibitor and anti-PD-1 antibody respectively, the combination therapy dramatically enhanced this inhibition on both tumor size and weight, and extended the survival of tumor-bearing mice." (PMID 38402237, 2024). "Finally, FFAR2 inhibition overcame resistance to immune checkpoint blockade through enhancing the recruitment and cytotoxicity of tumor-infiltrating T cells." (PMID 38402237, 2024). "Thus, FFAR2 was demonstrated to be a key regulator for pro-tumor MDSCs in reshaping immune suppressive TME." (PMID 38402237, 2024). "Moreover, pharmaceutical inhibition of FFAR2 signaling significantly facilitated the immune checkpoint blockade (ICB) mediated tumor suppression, suggesting the great potential of FFAR2 as a novel target for cancer immune therapy." (PMID 38402237, 2024). "Moreover, immunofluorescent staining showed that the infiltrating Gr-1+-MDSC was significantly decreased in tumor from FFAR2 inhibitor or combination therapy group." (PMID 38402237, 2024). "Moreover, tumor-infiltrating immune cells analysis showed that whole or myeloid Ffar2 gene deletion markedly reduce MDSCs accumulation, but increases CD4+ and CD8+ T cell infiltration in tumors." (PMID 38402237, 2024). "FFAR2 is an epigenetic tumor suppressor that could be activated by butyrate and is required for butyrate to suppress HDAC expression and hypermethylation of inflammation suppressors." (PMID 36282328, 2022). "In addition, FFAR2 is vital for butyrate to suppress HDAC expression and induce the hypermethylation of inflammation suppressor genes, which suggested that FFAR2 is an epigenetic tumor suppressor." (PMID 34691992, 2019). "Therefore, FFAR2 may serve as a potential new target to eliminate pathologically activated MDSCs and reverse immunosuppressive tumor microenvironment, which has great potential in improving clinical outcomes of cancer immunotherapy." (PMID 38402237, 2024). "However, the role of FFAR2 in tumor immune evasion through cancer cells exacerbated endogenous fatty acids remains unclear." (PMID 38402237, 2024). "Therefore, we investigated whether the effects of FFAR2 on tumor growth were through MDSCs, TAMs and DCs." (PMID 38402237, 2024). "Although, FFAR2 has been found to play a critical role in migration of polymorphonuclear leukocytes (PMNs) and regulate the size and function of Treg pool through gut microbiota-derived SCFAs, the function of FFAR2 in MDSCs mediated tumor immune evasion remains unclear." (PMID 38402237, 2024). "Secretin tumour cell line 1 enteroendocrine cells were treated for 24 or 48 h with toll-like receptor agonists (toll-like receptor 4 selective lipopolysaccharide; toll-like receptor 2 selective Pam3CysSerLys4) and the free fatty acid receptor 2/3 agonists butyrate, propionate and acetate." (PMID 37953845, 2023). "However, the role of FFAR2 in tumor infiltrated immune cells remains unknown." (PMID 38402237, 2024). "Recent studies have reported the oncoprotective effects of free fatty acid receptor 2 (FFAR2), the ligands of which are SCFAs, on several types of neoplasia." (PMID 34443546, 2021).
tumor (continued). "Additionally, co-injection of Ffar2−/− MDSCs markedly delayed tumor growth than Ffar2+/+ MDSCs both in LLC and B16F10 tumor models." (PMID 38402237, 2024). "Whereas, the tumor growth of LLC and B16F10 could only be notably accelerated by NaAc in Ffar2+/+ mice." (PMID 38402237, 2024). "For instance, DCs expressing FFAR2 inhibit their expression of IL-27 to sustain murine intestinal mucosal barrier integrity, reduce tumor bacterial burden, and suppress CD8+ T cell exhaustion, thereby restraining tumor initiation." (PMID 38903520, 2024). "FFAR2 and FFAR3 might participate in tumour suppression through propionate and butyrate, influencing cell proliferation and inducing apoptosis." (PMID 36765550, 2023). "It has been proposed that FFAR2 and FFAR3 might participate in tumour suppression through propionate and butyrate, influencing cell proliferation and inducing apoptosis." (PMID 33716996, 2021). "However, these conclusions should be taken carefully, because this organoid model experimental study does not consider variables such as host and tumour microenvironment, namely on the bioavailability of SCFAs and the expression of FFAR2 and FFAR3." (PMID 33716996, 2021). "Meanwhile, NaAc and FFAR2 inhibitors could not influence the proliferation and survival of LLC and B16F10 tumor cells in vitro." (PMID 38402237, 2024).
cancer (38 papers, 2017 to 2025). A tumor composed of atypical neoplastic, often pleomorphic cells that invade other tissues. "The aim of our study was to evaluate the anti-cancer effect of FFAR2 and FFAR4 stimulation by selective synthetic agonists in in vitro and in vivo models of CRC." (PMID 39432182, 2024). "Collectively, these data suggest the predominant role of Gαq/Calcium/PPAR-γ/Arg1 signaling as well as L-Arginine consumption in FFAR2 mediated immune suppression, which have great potential to be targets for cancer immunotherapy." (PMID 38402237, 2024). "The control group presented higher expression levels of SCFA and FFAR2, while the cancer group had higher levels of TNFAIP8, IL6, and STAT3." (PMID 37893122, 2023). "To elucidate the impact of FFAR2 in cancer in general, we mined the literature and compared the expression level in different cancer entities." (PMID 32517300, 2020). "However, when comparing the FFAR2 and PH groups, the anti-cancer cachexia effect of PH involves both modified gut microbiota and metabolites, rather than relying solely on an SCFA-dependent mechanism." (PMID 40129936, 2025). "Notably, the free fatty acid receptors FFAR1 (GPR40), FFAR2 (GPR43), FFAR3 (GPR41), and FFAR4 (GPR120) have the potential to bridge the genetic and environmental factors associated with cancer." (PMID 38243188, 2024). "Additionally, we showed that TNFAIP8, the IL-6 cytokine receptor, and IL-6-activated STAT3 pathway activity increased following FFAR2 reduction in the all cancer group." (PMID 37296861, 2023). "The combined administration of these compounds with SCFAs or FFAR2 agonists may result beneficial in cancer therapy." (PMID 33113952, 2020). "The mechanisms involved in cancer silencing of FFAR2 are still unknown, but it has been shown that the receptor undergoes important post-translational modifications." (PMID 33113952, 2020). "Activation of G protein-coupled receptors (GPCRs), such as FFAR2 (GPCR43), by SCFAs can trigger signaling cascades that ultimately suppress cancer cell growth and migration." (PMID 40869155, 2025). "Altogether, our results demonstrate that the acetic acids/FFAR2 axis enhances MDSCs mediated immunosuppression through Gαq/calcium/PPAR-γ/Arg1 signaling pathway, thus contributing to cancer progression." (PMID 38402237, 2024). "These SCFA also act in downstream signaling pathways in CRC cells and in non-cancer cells including IEC and immune system cells through interaction with G protein coupled receptors (FFAR2/GPR43, FFAR3/GPR41, GPR109a, and Olfr78)." (PMID 31157230, 2019). "Furthermore, we used free fatty acid receptor FFAR2 (a crucial SCFA signaling molecule) agonist to investigate the role of gut microbiota metabolites, such as SCFAs, in the treatment of cancer cachexia, with comparisons to PCPs." (PMID 40129936, 2025). "In summary, our study suggested a novel strategy to eliminate the pathologically activated MDSCs specifically by targeting FFAR2 without excessive off-target effects which have great potential in clinical application for cancer immunotherapy." (PMID 38402237, 2024). "In the same context, this study suggested that alteration in specific bacteria may shift the expression of FFAR2 and SCFA, which could influence cancer initiation via cytokine receptor activation and chronic inflammation." (PMID 37296861, 2023). "Previous studies suggest that FFAR2 and FFAR3 are involved in the regulation of cancer development." (PMID 29049318, 2017). "Taken together these studies support a model by which reduced expression of FFAR2 and FFAR3 may contribute to cancer progression." (PMID 29049318, 2017). "F. nucleatum is a significant producer of SCFAs, especially propionate and butyrate, and while there has been previous evidence of F. nucleatum’s ability to activate neutrophils via the FFAR2 pathway, there is no direct evidence of F. nucleatum’s effect on cancer development via SCFAs." (PMID 37893122, 2023).
cancer (continued). "Additionally, the agonist of free fatty acid receptor 2 (FFAR2)—a crucial short-chain fatty acid (SCFA) signaling molecule—was used to investigate the role of gut microbiota metabolites, specifically SCFAs, in the treatment of cancer cachexia, with comparisons to PCPs." (PMID 40129936, 2025). "Moreover, the Acetic acids/FFAR2 axis enhanced the expression of Arg1 through the Calcium/PPAR-γ pathway, suggesting inhibitors or modulators targeting Calcium/PPAR-γ or SCFA excess in combination with anti-PD-1 antibodies will have potential clinical value in improving cancer treatment." (PMID 38402237, 2024). "FFAR2 agonist, 4-CMTB, and FFAR4 agonist, GSK137647 significantly decreased both non-cancer (CCD 841 CoN) and cancer (SW-480) cell growth at the concentrations 10–200 μM as compared to untreated cells." (PMID 39432182, 2024).